PDGFRA (platelet derived growth factor receptor alpha)
Diseases named in the same sentence as PDGFRA in open-access papers (continued):
Sharing a sentence is not in itself a finding about the gene and the disease.
tumor (945 papers, 2004 to 2026). "Secondary mutations in KIT and PDGFRA, compensatory activation of parallel signaling pathways, and tumor microenvironment-mediated resistance continue to limit long-term efficacy of current TKIs." (PMID 41517566, 2026). "More models were established from donor tumor samples carrying a KIT mutation than from those carrying a PDGFRA mutation, corresponding with the lower incidence and less aggressive behavior of PDGFRA-related disease." (PMID 39853155, 2025). "PDGFRA encodes a receptor that controls cell proliferation and fibroblast activation, playing a key role in tumor-associated fibrosis." (PMID 40817072, 2025). "The amplified and mutated PDGFRA gene contributes to uncontrolled signaling that promotes tumor growth." (PMID 40868137, 2025). "In summary, imatinib resistance in GISTs arises from both intrinsic and acquired mechanisms, most notably through secondary mutations in KIT or PDGFRA and tumor heterogeneity." (PMID 40733131, 2025). "Imatinib’s efficacy in GISTs stems from its ability to inhibit two key receptor tyrosine kinases, c-KIT and PDGFRA, both of which are frequently mutated in these tumours." (PMID 41426918, 2025). "This dual involvement of telocytes and PDGFRA mutations helps reconcile the paradox of IFPs: a lesion that behaves clinically as a benign process yet exhibits clear molecular features of neoplasia." (PMID 41562800, 2025). "Our previous research showed that PDGFRα expression is linked to the morphology and vascular features of low-grade NENs, correlating with lower microvessel density and reduced tumor growth." (PMID 40806365, 2025). "Overexpression of PDGFRα and PDGFRβ was significantly associated with unfavorable tumor characteristics and higher tumor burden." (PMID 40434293, 2025). "Sarcoma European Latin‐American Network (SELNET) guidelines for GIST recommend KIT and PDGFRA tumor mutational analysis for candidates for systemic therapy but does not provide specific guidelines on SDH IHC testing." (PMID 39927693, 2025). "In Case 1, the mutation profiles of the two tumor lesions shared only a PDGFRA and DNMT3A missense mutation and a CHEK2 frameshift mutation." (PMID 40589631, 2025). "A meta-analysis including 1,487 GIST patients found that the KIT mutations compared with PDGFRA mutations and wild-type tumors were associated with an increased risk of tumor size of >5 cm and higher mitotic activity." (PMID 40703587, 2025). "These tumours are primarily driven (around 80%) by mutations in the c-KIT or PDGFRA genes, leading to the activation of tyrosine kinase pathways that promote tumour growth and survival." (PMID 41426918, 2025). "Downregulating the expression of ERG in HPCs significantly reduces the number of PDGFRα+ CAFs and the infiltration of tumour-associated macrophages in HCC, thereby suppressing hepatocarcinogenesis." (PMID 39827226, 2025). "PDGFRA is a known oncogene, encoding a cell surface tyrosine kinase receptor protein, and its alterations have been described in many neoplasms." (PMID 38401149, 2024). "GIST is a highly heterogeneous tumor including various molecular entities with mutually exclusive gain-of-function mutations in KIT or PDGFRA mostly." (PMID 38443340, 2024). "In contrast, spotty ECM texture is linked to higher overall frequency of tumor cells and mildly related to presence of cells with co-amplified PDGFRA/EGFR." (PMID 38805346, 2024). "The NGS results of the tumor cells showed that amino acids 842–843 of the platelet-derived growth factor receptor alpha (PDGFRA) were deleted, and base A was mutated to base T, inducing the mutation of isoleucine to phenylalanine." (PMID 37454137, 2023).
tumor (continued). "It demonstrated clinical benefit in Chinese patients with GIST bearing the PDGFRA D842V mutation and promising preliminary anti-tumor activity as fourth- or later-line monotherapy." (PMID 36477870, 2023). "Three tumours (14%) had oncogenic PDGFRA exon 18 mutations, and 18 tumours (86%) had KIT exon 11 mutations." (PMID 37622176, 2023). "Avapritinib was generally well tolerated and showed marked anti-tumor activity in Chinese patients with GIST bearing PDGFRA D842V mutations and notable efficacy as fourth- or later-line monotherapy (ClinicalTrials.gov Identifier: NCT04254939)." (PMID 36477870, 2023). "An exception is represented by patients with tumours harbouring the imatinib-insensitive PDGFRA D842V mutation who would be better treated with avapritinib." (PMID 37627109, 2023). "In epithelioid and mixed variants of GISTs, the expression of KIT/PDGFRA-mutant isoforms is associated with the anatomical site of the tumor." (PMID 37046997, 2023). "Gastrointestinal stromal tumours (GIST) are the most common mesenchymal derived tumours and most patients have mutations in the c-kit or platelet derived growth factor receptor alpha (PDGFRA) gene." (PMID 36690935, 2023). "Familial GIST is an inherited neoplastic disease with multiple GISTs throughout the GI tract caused by germline mutations in KIT gene or PDGFRA gene." (PMID 37870660, 2023). "Most GISTs have gain-of-function mutations in c-KIT or platelet-derived growth factor receptor alpha that promote tumor cell proliferation and inhibit tumor cell apoptosis." (PMID 35502427, 2022). "PDGFRA, platelet-derived growth factor receptor alpha, which encodes a cell surface tyrosine kinase receptor, plays a crucial role in organ development, wound healing, and tumor progression." (PMID 35592524, 2022). "Studies have shown that novel tyrosine kinase inhibitors (TKIs), avapritinib and ripretinib, target the PDGFRA D842V mutation in GISTs and provide objective responses and long-term tumor control." (PMID 36119525, 2022). "Conversely, our study supports that D842V GISTs represent a tumor subset with distinctive biological behavior compared to other GISTs with non-D842V PDGFRA mutations." (PMID 36293105, 2022). "Similar to the archival tumor samples, mutations in PDGFRA or BRAF were rare (n = 2 and n = 0, respectively)." (PMID 35050442, 2022). "Both in vitro proliferation and in vivo studies indicated that nilotinib exhibited anti-tumor activity against the PDGFRA V561D mutation but significantly reduced efficacy against PDGFRA D842V mutation." (PMID 36119525, 2022). "KIT and PDGFRA are the main driver mutations but insufficient to promote tumor progression from low- to high-risk GISTs." (PMID 35965531, 2022). "The targets of action of anlotinib include VEGFR2/3, PDGFRα/β associated with tumor vascular survival ability (VSA), and FGFR1-4 associated with fibrosis." (PMID 35847852, 2022). "Thereafter, we analyzed the difference in the enrichment of tumor-infiltrating immune cell subpopulations between the CN gain and No CN gain groups among the six cancer species in which the CN gain of PDGFRA pathway was significantly associated with OS." (PMID 35212838, 2022). "Clustered stromal cells corresponded to endothelial cells (positive for PECAM1/CD31, VWF), normal fibroblasts (FN1, EGFL6), tumor-associated fibroblasts (TAFs; PDGFRA, ADH1B), and thymic epithelial cells (TECs; KRT19, S100A14)." (PMID 35869073, 2022). "Abundant infiltrating immune cells were found in PDGFRA-mutant GISTs and PD-L1 expression was negatively associated with tumor size." (PMID 34557343, 2021). "As the main GIST drivers, gain-of-function mutations in KIT or PDGFRA are closely associated with not only tumor development and progression but also therapeutic response." (PMID 34805171, 2021).
tumor (continued). "In this study, we comprehensive analyzed genomic changes in GIST using WES, and identified a series of novel variants in KIT/PDGFRA or other tumor-related genes, and these genes are enriched in several DNA repair- or metabolism-related pathways." (PMID 34805171, 2021). "At diagnosis, 80% have a mutation in KIT and 10% in PDGFRA, resulting in tyrosine kinase activation and tumor cell proliferation." (PMID 34552011, 2021). "The association between CD133 and PDGFRα with distinct molecular subtypes of GB and supports previous findings that different molecular subtypes can co-exist within the same tumor." (PMID 35052687, 2021). "Nevertheless, ERK activation by PDGFRβ signaling pathway cannot compensate the loss of HIF1α-PDGFD-PDGFRα-AKT network for GBM tumor growth because knockout of either HIF1A or PDGFD or PDGFRA in U251 cells eradicated the tumor growth." (PMID 34470658, 2021). "We have previously developed and characterized a unique multistep KSHV tumorigenesis model in which cells explanted from a KSHV (+) tumor that lose the episome can form KSHV (−) tumors driven by host mutations such as the PDGFRA-D842V." (PMID 34222014, 2021). "PDGFRA gene was mutated within a tumor that originated within the white matter of the parietal lobe with the predominant normal gene expression being found in pons, thalamus, and claustrum." (PMID 34257334, 2021). "Patients with KIT mutated GISTs tended to have a larger tumor size and a higher mitotic index and risk grade as compared with those with PDGFRA-mutant and WT GISTs." (PMID 34956906, 2021). "We developed patient-specific SiMSen-Seq panels that target the patient's tumor-specific mutation in either KIT or PDGFRA, as well as mutations related to imatinib and sunitinib resistance." (PMID 34552011, 2021). "Compared with mice transplanted with cells transduced with LentiCRISPRv2-GFP encoding a control sgRNA, animals xenografted with ASCL1 and SOX11 gene-edited cells survived longer, which was associated with reduced tumor PDGFRA expression at endpoint." (PMID 32142668, 2020). "Several patients experienced clinical benefit with tumor mutations in cKIT, CSF-1R, PDGFRα, PDGFRβ, VEGFR1, VEGFR2, FLT3, FGFR2, RET, and TrkA." (PMID 32292573, 2020). "We have generated a unique multistep KSHV tumorigenesis model in which cells explanted from a KSHV(+) PDGFRA (+) tumor that lose the episome can form KSHV (-) tumors driven by host mutations such as the PDGFRA-D842V." (PMID 32603362, 2020). "The amplification of EGFR and PDGFRA genes are often considered to be among the key mutations driving oncogenesis and tumour growth." (PMID 33120534, 2020). "Because the tumor had a PDGFRA mutation (D842V substitution), imatinib was suspected to lack efficacy to the tumor." (PMID 32703220, 2020). "With regards to clinicopathological features, PDGFRα overexpression observed in 45% of epithelial colorectal ADK was significantly associated with tumor diameter ≤ 5 cm (P = 0.048)." (PMID 33213472, 2020). "Our results showed an association between PDGFRα expression in tumor and stromal cells (P < 10−3, respectively)." (PMID 33213472, 2020). "We eventually diagnosed the tumor as a GIST because the PDGFRA mutation was confirmed by Sanger sequencing and CD117/DOG1 were positive in the IHC test." (PMID 32005261, 2020). "In EGIST, the degree of KIT and PDGFRA mutations varies on where the location of the tumor is, and it is suggested that omental EGIST is similar to gastric GIST." (PMID 32703220, 2020). "Determination of the tumor genotype is recommended before initiating adjuvant therapy; furthermore, the mutation in PDGFRA exon 18 (D842V) is resistant to Imatinib therapy." (PMID 33489517, 2020). "GISTs with PDGFRA exon 18 mutations had smaller tumour size than cases with KIT exon 9 and exon 11 mutations (p=0.01)." (PMID 31538651, 2020).
tumor (continued). "The association between PDGFRα overexpression in both tumor and stromal adenocarcinoma cells with RAS wild type status suggests its potential role in anti-EGFR therapy resistance and the relevance of using it as specific or adjuvant therapeutic target." (PMID 33213472, 2020). "Of 22 multiple sporadic GIST patients with at least one lesion assessed as intermediate and high risk mentioned in the literature, 13 cases showed tumor multiplicity on KIT/PDGFRA mutation analysis, excluding them as metastatic GISTs." (PMID 32408889, 2020). "Activating mutations in cKIT and PDGFRα are common in gastrointestinal stromal tumors and are thought to play crucial roles in tumor initiation." (PMID 32292573, 2020). "The following tumor mutations were reported in patients with clinical benefit: cKIT (n = 1), CSF-1R (n = 1), PDGFRα (n = 2), PDGFRβ (n = 1), VEGFR1 (n = 1), VEGFR2 (n = 2), FLT3 (n = 1), FGFR2 (n = 2), RET (n = 1), and TrkA (n = 1)." (PMID 32292573, 2020). "In patients with GISTs with a PDGFRA D842V mutation, avapritinib resulted in more tumour shrinkage in almost all cases (98%), with an ORR of 84%." (PMID 32462367, 2020). "Other variants detected in this tumor, such as those inFGFR3,PDGFRA,KDR (c.1416A>T),CSF1R,EGFR,RET,HRAS,PIK3CA,FLT3 (c.1310-3T>C), andSMAD4, are benign." (PMID 32612806, 2019). "Sanger sequencing revealed that the GIST tumor cells contained a deletion mutation (c.2527_2538 del12,843–846del4), which was located in exon 18 of PDGFRA." (PMID 31647020, 2019). "Although baseline demographic features and KIT or PDGFRA exon mutation were similar between studies, there were differences in tumor burden and surgical intervention." (PMID 30693663, 2019). "The tumor cells of GISTs contained a deletion mutation (c.2527_2538 del12,843–846del4), which was located in exon 18 of PDGFRA." (PMID 31647020, 2019). "Attempts to elucidate the genomic profile of this rare tumor have been accomplished by only a few studies, but have emphasized the involvement of PDGFRA, a gene encoding tyrosine kinase receptors for platelet-derived growth factor." (PMID 31480474, 2019). "Among the downregulated genes in PMDs are EGFR (epidermal growth factor receptor) and PDGFRA (platelet-derived growth factor receptor α) that have tumor promoting mutations." (PMID 30988298, 2019). "Usually, these tumours arise from driver-mutations in KIT or PDGFRA genes and it is nowadays widely accepted that KIT protein expression is a hallmark of GIST." (PMID 29707131, 2018). "In this study, we characterize 16 novel PDGFRA mutations identified from different tumor types and identify three previously uncharacterized activating mutations that promote cell survival and proliferation." (PMID 30389923, 2018). "For example, the loss-of-function SDH complex mutations are considered to play a critical role in tumor initiation of a minor subset of GISTs that exhibit distinct clinicopathological features from GISTs with KIT- or PDGFRA-mutations." (PMID 30388854, 2018). "Loss of mutations from primary tumor to metastases were identified in case 5 (PDGFRA) and case 9 (FGFR2)." (PMID 29731974, 2018). "Here, the authors perform functional characterization of 16 novel PDGFRA mutations identified from different tumor types and demonstrate that a neomorphic PDGFRA extracellular domain driver mutation is resistant to PDGFRA targeted therapies." (PMID 30389923, 2018). "High primary tumour PDGFRα was associated with increased risk of central nervous system (CNS) recurrence." (PMID 29380207, 2018). "Our study showed that PDGFRα expression in tumor site was associated with increased Lrat expression in tumor site." (PMID 28465473, 2017). "Together, some authors, including Tajima, observed that GISTs with PDGFRA mutations are frequently characterized by epithelioid pattern, myxoid stroma, mast-cells infiltrating tumor, multi-nucleated neoplastic cells and some rhabdoid cells." (PMID 27738305, 2017).
tumor (continued). "Strong PDGFRα expression in tumor site was associated with decreased overall survival after curative HCC resection (p=0.001)." (PMID 28465473, 2017). "In accordance with other previous studies, our study also demonstrated that strong PDGFRα expression in tumor sites was associated with poor survival outcome after HCC resection." (PMID 28465473, 2017). "Direct Sanger sequence analysis of DNA from this tumor by the FCCC Clinical Molecular Genetics Laboratory detected an exon 18 D842V mutation in the PDGFRA gene." (PMID 28768491, 2017). "This accounted for 38/351 patients (10.8%) in the prospective cohort (37 CRC patients with activating KRAS or NRAS mutations and one GIST patient with a PDGFRA D842V mutation) and is also an important outcome of tumour testing." (PMID 28196074, 2017). "Tsc2−/− MEFs transfected with lentiviral vector encoding PDGFRα or empty vector were subcutaneously injected into the right anterior armpit of nude mice, and then tumor growth was monitored." (PMID 28903387, 2017). "Strong PDGFRα expression in the tumor lesions was associated with decreased survival after curative HCC resection." (PMID 28465473, 2017). "Additional mutation analysis was performed on the biopsy taken at diagnosis and revealed a PDGFRα exon 18 (NM_006206.5: c.2527_2538del; p.(I843_D846del)) mutation (the average coverage is ∼2500 reads in tumor DNA with neoplastic content of 95%)." (PMID 29312652, 2017). "Tumor cells are generally spindled or mixed spindled/epithelioid, and these GISTs, with notable exceptions such as the PDGFRA D842V mutation discussed here, generally respond well to front-line therapy with the RTK inhibitor IM." (PMID 28768491, 2017). "The high expression of PDGFRA is associated with group II tumours, and is associated with the sensitivity to tyrosine kinase inhibitors." (PMID 27607470, 2016). "By analyzing the KEGG (Kyoto Encyclopedia of Genes and Genomes) pathway annotation in these data sets, we revealed that several pathways were significantly associated with PDGFRα and PDGFRβ expression, respectively, in the five separate tumor cohorts." (PMID 25576913, 2015). "Mutations in platelet-derived growth factor receptor α (PDGFRA; chromosome 4q12) have been indicated to be involved in the development of this tumor." (PMID 25435986, 2015). "The discovery that the vast majority of GISTs have characteristic activating mutations in c-KIT (75–80%) or PDGFRA (5–15%) radically changed the management of these tumours by the approval of the use of tyrosine-kinase inhibitors." (PMID 26075122, 2015). "The tumor probably arises from KIT or platelet-derived growth factor receptor A (PDGFRA) gene mutations in precursor cells that normally give rise to the interstitial cells of Cajal." (PMID 24587795, 2014). "PDGFRα –mediated paracrine signaling between tumor cells and stromal fibroblasts was found to be a principal mechanism for stroma recruitment and tumor growth especially when tumor cells are deficient in VEGF production." (PMID 24423144, 2014). "Specifically a marked increase in PDGFRα expression was associated with a shorter time to progression and less tumor regression based on RECIST criteria." (PMID 24732172, 2014). "Oncogenic mutations in KIT or PDGFRA have been identified as central tumor-initiating events in many GISTs." (PMID 23902675, 2013). "The primary tumor actually has loss of chromosome 4q where the PDGFRA gene is located, whereas the xenograft becomes diploid again at this chromosomal arm." (PMID 23527265, 2013). "Inhibition of PDGF in preclinical models of non-small cell lung cancer by treatment with a neutralizing PDGFRα antibody (MEDI-575) caused a significant decrease in stromal fibroblast content but had only minor effect on tumor cell proliferation." (PMID 24359404, 2013).